IL2 (interleukin 2)
Diseases named in the same sentence as IL2 in open-access papers (continued):
Sharing a sentence is not in itself a finding about the gene and the disease.
melanoma (continued). "Combining IL-2 with PD-1 is more attractive than ipilimumab, owing to the better safety profile and antitumor activity of PD-1 blockade in patients with melanoma." (PMID 36845705, 2023). "Among melanoma patients in the PROCLAIM registry who were treated with HD IL-2 after prior treatment with ipilimumab or an anti-PD1 antibody, the response rates were 21% (11 of 52 patients) and 22.5% (9 of 40 patients), respectively." (PMID 36845705, 2023). "IL-2 and IFNα were the first immunomodulators used to treat melanoma and renal cell carcinoma, and molecules that target the IL-2 and IFNAR pathways are FDA-approved for some cancer types." (PMID 37274739, 2023). "The use of IL-2 and IL-12 for the treatment of melanoma has been extensively studied in preclinical models, including the delivery of plasmids encoding IL-2 and IL-12 using gene electrotransfer (GET)." (PMID 37376422, 2023). "Nevertheless, in IL-2 immunotherapy, co-treatment with A. muciniphila strengthened IL-2 antitumor effects in both subcutaneous melanoma and colorectal tumor-bearing mice." (PMID 38045608, 2023). "IL-2 has been widely used as a cytokine approved for melanoma and renal cell carcinoma, but high doses of IL-2 have side effects." (PMID 37513483, 2023). "At our center, we began treating a substantial number of stage IV melanoma patients with interleukin-2-based immunotherapy in 2003, and in 2007 we began participation in clinical trials of checkpoint inhibitor immunotherapy." (PMID 38111529, 2023). "Considering its role in activating the immune system of cancer patients, application of interleukin-2 (IL-2) was approved for treatment of patients with metastatic renal cell carcinoma and malignant melanoma." (PMID 36742134, 2023). "TIL treatment was first studied clinically as therapy for melanoma over 20 years ago in combination with high-dose IL-2, before modern checkpoint blockade immunotherapy was introduced." (PMID 36831449, 2023). "A more recent study, performed in Israel, found that 50% of advanced, chemotherapy and IL-2 refractory melanoma patients achieved radiologic response to short-term cultured bulk tumour-infiltrating lymphocyte therapy with a tolerable toxicity profile." (PMID 37371056, 2023). "A case reported that intratumoral adoptive immunotherapy with TILs in patients with melanoma, in combination with subcutaneous infusion of IL-2 and a single intratumoral injection of a low dose of IFNα, led to consistent tumor regression." (PMID 38006049, 2023). "Today, IL-2 is still being utilized in certain cases to treat advanced melanoma and kidney cancer, particularly in combination with other immunotherapeutic agents to enhance their efficacy." (PMID 37256141, 2023). "A high dose of IL-2 induced a durable anti-tumor response, especially in advanced renal cell carcinoma and melanoma, but severe toxicity was the main obstacle to successful treatment." (PMID 38139110, 2023). "These TILS were isolated from melanoma surgical specimens, expanded in vitro with IL-2 for several weeks, and subsequently reintroduced into melanoma patient, resulting substantial tumour regressions." (PMID 38098489, 2023). "Several cytokines, including monocyte chemoattractant protein 1 (MCP-1), TNF-α, IL-6 and IL-2 have been reported to be predictive biomarkers for the response of melanoma patients to ICI treatment or for melanoma metastases." (PMID 36768978, 2023). "There was one response observed (11%) in a patient with PD-1 refractory melanoma who was treated with HD IL-2." (PMID 36845705, 2023). "To date, several transcription factors have been shown to control the activity of the BCL-2 promoter, for example, Aiolos in IL-2-deprived T cells, Mitf in the context of melanoma cell viability, and Pi in the context of B-cell differentiation." (PMID 38092733, 2023). "Melanoma sensitivity towards T cells was investigated via cytotoxicity, cell viability, and IL-2 assays employing CTLL-2 cells." (PMID 37731735, 2023).
melanoma (continued). "We observed a steady increase in the use of immunotherapy for metastatic melanoma from 1.58% in 2011, the first year of approval of the new-generation immunotherapy for melanoma since interleukin-2, to 58.03% in 2018." (PMID 37442992, 2023). "Maltol augmented sensitivity to CTLL-2 cell-regulated melanoma destruction, leading to an increase in IL-2 production." (PMID 37731735, 2023). "Clinical trials have investigated the use of IL-2 alone or in combination with other agents, such as checkpoint inhibitors, in treating various types of cancer, including melanoma and renal cell carcinoma." (PMID 37516849, 2023). "There is a paucity of high-quality data examining the pharmacokinetics of intralesional IL2 in the context of in-transit or metastasic melanoma." (PMID 37182189, 2023). "Interferon alpha has been approved for melanomas, and high-dose interleukin-2 (HDIL-2) has been approved for renal cell carcinomas and melanomas." (PMID 37111620, 2023). "Administration of IL-2 for advanced renal cell carcinoma and melanoma, and IFN-α for leukemia and melanoma induced anti-tumor immune responses leading to FDA-approval, but toxicity of these cytokines is significant, making these drugs not very attractive." (PMID 37079257, 2023). "We observed very similar protective effects of combinational therapy of Dox plus IL-2/JES6 in a B16F10 melanoma model." (PMID 36705564, 2023). "Interleukin-2 (IL-2) administration represented the first effective immunotherapy for patients with melanoma." (PMID 38139110, 2023). "The efficacy of human NK cells that were expanded ex vivo using feeder cells + IL-2 + IL-21 was analysed in NSG mice injected with a human melanoma cell line." (PMID 37388731, 2023). "Since the 1990s, it has been known that responses to high dose interluekin-2 (HD IL-2) in melanoma patients are low in frequency but exceptionally durable." (PMID 36845705, 2023). "We performed a single-institution retrospective study of stage IV melanoma patients treated with interleukin-2 or checkpoint inhibitors over the period from 1992 to 2013." (PMID 38111529, 2023). "For instance, high-dose Interleukin-2 (IL-2) has been used in the treatment of certain types of kidney cancer and melanoma, albeit with variable success and significant toxicity." (PMID 37420216, 2023). "In some mouse tumor models, the therapeutic effects of IL-2-based treatment only manifest in combination with immunogenic chemotherapy (B16F10 melanoma in C57BL/6 mice and BCL1 leukemia in BALB/C mice) or irradiation (K5L1940 adenocarcinoma in C57BL/6 mice)." (PMID 37827864, 2023). "For instance, IL-2-based immunotherapy has demonstrated increased efficacy in malignancies such as melanoma and renal cell carcinoma (RCC), attributed to their higher expression of IL-2R." (PMID 37516849, 2023). "Before the advent of ICI, immunotherapy in the treatment of advanced melanoma consisted of the use of high-dose IL-2 and adoptive cell therapy with autologous tumor-infiltration lymphocytes, with ORR of about 15% and up to 50%, respectively." (PMID 36768978, 2023). "For instance, a high dose of IL2 is approved for the treatment of melanoma and renal cell carcinoma, while the same payload given at a low dose is used for treating chronic inflammatory conditions." (PMID 36839699, 2023). "In melanoma, IT interleukin-2 (IL-2) has been explored as an immunotherapeutic approach for LMD since the early 1990s15." (PMID 36997799, 2023). "Melanogenesis can reduce the killing effect of cyclophosphamide and IL-2 activated peripheral blood lymphocytes on melanoma cells and make them resistant to chemotherapy drugs and lymphotoxicity." (PMID 36901791, 2023). "As CIML NK cells have been shown to express CD25, mice bearing the melanoma xenograft were given serial boosts of IL-2 to support persistency and activation of transferred NK cells." (PMID 37388731, 2023).
melanoma (continued). "In this study, four of seven patients from the group treated with combined DC therapy and IL-2 showed delayed type IV hypersensitive (DTH) reaction against melanoma cell lysates." (PMID 36631633, 2023). "For instance, T-VEC, rose Bengal, imiquimod, and IL-2 are used in melanoma, whereas transarterial embolisation, chemoembolisation or radioembolisation, RFA, and MWA are all effective for liver metastases." (PMID 37444450, 2023). "We showed here that exogenous expression of ∆Ex3PD1 was sufficient to partially reverse inhibition of IL-2 by melanoma and enhance killing of cholangiocarcinoma cells." (PMID 37973660, 2023). "The ginsenoside Rh2 has been reported for its activities in improving IL-2 production in vitro and increasing the number of T cells in a melanoma mouse model." (PMID 38202694, 2023). "These response rates are comparable to historical controls; these data suggest that HD IL-2 treatment retains its effectiveness in patients whose melanoma is refractory to ipilimumab or anti-PD-1 treatment." (PMID 36845705, 2023). "Despite its limited use owing to toxicities, the results with IT IL-2 demonstrate that long-term disease control and survival in melanoma LMD patients is possible with IT immunotherapy and warrants further investigation with more modern immunotherapy agents." (PMID 36997799, 2023). "IL-2/CD25 transdimers also improved the frequency of neoantigen-specific T cells following administration of a TSA vaccine containing four B16-F10 melanoma neoantigens and Poly-IC." (PMID 35651800, 2022). "In a small group of advanced melanoma patients, the use of IL-2 as adjuvant therapy showed excellent results in suppressing metastases." (PMID 35565234, 2022). "IL-2, IL-4, and IL-12 were the most widely used cytokines as vaccine adjuvants, especially IL-2, which was used as an immune adjuvant in many kinds of cancer types, such as lung cancer, colorectal cancer, and melanoma." (PMID 35967400, 2022). "The first anticancer immunotherapeutic agent was used T cell growth factor interleukin 2 (IL-2), where IL-2 treatment showed significant tumor suppression by enhancing T-cell activation in patients with metastatic kidney cancer and melanoma." (PMID 36003395, 2022). "EZH2 inhibition can cooperate with anti-CTLA-4 and IL-2 immunotherapy to inhibit the growth of melanoma." (PMID 35907846, 2022). "Initially Food and Drug Administration−approved for treatment of metastatic renal cell carcinoma and melanoma in the 1990s, before the resurgence of Treg biology, high doses of IL-2 are used as stimulatory immunotherapy." (PMID 35699942, 2022). "Several studies showed neoadjuvant vaccination, such as IL-2 or dendritic cell infusions, increased antitumor effectiveness of IR and resulted in an increased immune response in murine melanoma B78 tumor model or patients with soft tissue sarcoma." (PMID 36131926, 2022). "As reported, Interleukin-2 (IL-2), a growth factor for T and NK cells, plays a significant role in melanoma." (PMID 36588679, 2022). "The anti-tumor functions of IL-2-expanded Vδ2 T cells against several tumor cancer cell lines have been investigated including human neuroblastoma, myeloma, glioblastoma, melanoma, and renal adenocarcinoma and Burkitt ́s lymphoma." (PMID 36429001, 2022). "Originally, autologous T cells were isolated from melanoma resections, expanded in vitro with IL-2, before transplantation into patients with advance-stage melanoma." (PMID 36248881, 2022). "The application of IL-2-based therapeutics has brought great benefits to tumor patients, such as renal cell carcinoma and melanoma patients." (PMID 35812404, 2022). "Recombinant IL2 (Aldesleukin) is a powerful immunomodulator used to treat patients with metastatic renal cell carcinoma and malignant melanoma." (PMID 36085201, 2022). "In this model, B16 melanoma tumor cells were implanted into mice, followed by intra-tumoral or subcutaneous injections of rBCG::IL-2 or pBCG." (PMID 35632582, 2022).
melanoma (continued). "Due to its antitumor activity, a high-dose bolus of recombinant IL-2 has been used to treat melanoma for decades." (PMID 36405903, 2022). "In contrast to harnessing inflammatory conditions with LD IL-2, high-dose IL-2 (HD IL-2) formulations were used to combat malignant tumors, for example in melanoma and renal cancer patients." (PMID 35954285, 2022). "Recently, there are several cytokine drugs approved by FDA, such as high-dose IL-2 for the treatment of melanoma and kidney cancer, and IFN-α for the adjuvant treatment of stage III melanoma." (PMID 36209263, 2022). "IL-2 has a dual role in promoting a decrease, and tumor growth is impaired when melanoma-bearing mice are treated with IL-2 mutein." (PMID 35740551, 2022). "We have previously reported a beneficial role of intralesional Interleukin-2 (IL-2) in 9 melanoma patients developing new locoregional metastases under immunotherapy." (PMID 35158808, 2022). "One of the immunomodifiers developed for metastatic melanoma is interleukin 2 (IL2), which promotes the expansion of melanoma-specific T cells." (PMID 35401191, 2022). "A decrease in the frequencies of whole DCs and the cDC1 subset in tumor tissue suggests an explanatory mechanism of how the TBI/IL-2 combination reduces the additive effect in ACT of murine melanoma." (PMID 36497152, 2022). "This type of autocrine IL-2 circuit also shows similar dramatic therapeutic improvement in treating a different type of immune-excluded solid tumor – B16-F10 OVA intradermal melanoma tumors, treated with OT-1 TCR expressing T cells." (PMID 36520915, 2022). "The patient had excisions of two melanomas 20 years prior, followed by adjuvant treatment with tamoxifen, cisplatin, IL-2, and IFNa." (PMID 36045435, 2022). "In advanced melanoma cases, the gp100 cancer vaccine combined with IL-2 therapy significantly improved the median survival in patients as compared with the use of IL-2 alone." (PMID 36613591, 2022). "Papers related to IL-2 or ACT constitute a considerable share in melanoma immunotherapy, but the proportion has gradually decreased since 2013." (PMID 36698407, 2022). "When combined with antigen vaccines containing the melanoma TAAs gp100 or trp-1 and LPS or Poly-IC, IL-2/CD25 increased the frequency of effector and memory gp100-specific Pmel-1 CD8+ or TRP-1-specific TRP-1 CD4+ T cells post adoptive transfer." (PMID 35651800, 2022). "A previous study indicated that wild-type IL2 conjugated to tumor-specific antibodies administered as a monotherapy shows poor biodistribution and efficacy in the B16 melanoma tumor microenvironment." (PMID 35874707, 2022). "An analysis of eight different studies showed that the average survival time for patients with stage IV melanoma treated with interleukin-2 was 11.4 months, and about 10% of patients survived 5 years." (PMID 35406444, 2022). "High-dose recombinant IL-2 has been extensively tested in combination with melanoma antigen vaccines." (PMID 35651800, 2022). "Based on its immune-stimulatory activity, IL-2 has been used in the treatment of advanced melanoma and renal cell carcinoma, but its high toxicity precludes its extended use." (PMID 36059465, 2022). "In summary, these new developments in intralesional, IL-2-based therapies will further improve the outcome of certain melanoma patients harboring accessible, locoregional metastases." (PMID 35158808, 2022). "Treatment of metastatic renal cell carcinoma and melanoma with systemic IL-2 therapy specifically increased the number of tumor-infiltrating lymphocytes (TILs)." (PMID 36066630, 2022). "A similar infiltration and expansion of the CD8+ lymphocytes also seen in B16-F10 OVA melanoma tumors sampled 10 days after treatment with OT-1 T cells bearing the synthetic IL-2 circuit." (PMID 36520915, 2022). "Before 2010, massive-dose interleukin-2 (IL-2) therapy was the most commonly used immunotherapy for melanoma." (PMID 36698407, 2022).
melanoma (continued). "For example, IL-2 was approved for treating metastatic renal cell carcinoma and advanced melanoma in 1992 and 1998." (PMID 36297527, 2022). "IL-2 in particular was used as an immune adjuvant in many cancer types, such as lung cancer, colorectal cancer, and melanoma." (PMID 35967400, 2022). "Here, we demonstrate the effect of total body irradiation (TBI) pre-conditioning and IL-2 treatment post-conditioning in ACT of melanoma." (PMID 36497152, 2022). "The first therapeutic approaches in melanoma treatment involved the administration of IL-2 and interferon alone or in combination with chemotherapy." (PMID 35669438, 2022). "In the 1990s, high-dose interleukin 2 (IL-2) was used to treat advanced melanoma and renal cell carcinoma patients." (PMID 36140312, 2022). "in the 1960s, as well as the production, testing and approval of high doses of IL-2 (interleukin 2) for the treatment of metastatic kidney cancer and melanoma in clinical trials in the 1990s." (PMID 35669417, 2022). "Regarding the utilization of immunotherapies to treat NM due to melanoma, two separate cohort studies have demonstrated the use of IT interleukin-2 (IL-2) with varying chemotherapy combinations and reported a similar survival of 7.8–7.9 months, respectively." (PMID 36612116, 2022). "On the other hand, high doses of IL-2 has been found to produce durable antitumor responses, most benefiting patients with melanoma and renal cell carcinoma." (PMID 35596173, 2022). "A phase II study of ziv-aflibercept combined with interleukin-2 (IL-2) in patients with unresectable stage III/IV melanoma found an increase in PFS from 2.3 to 6.9 months." (PMID 35954441, 2022). "Although the extent of efficacy was lower than with TBI, IL-2 treatment enhanced the anti-melanoma effect of Pmel-1." (PMID 36497152, 2022). "Prior to checkpoint inhibitors, high-dose interleukin-2 (HD IL-2) demonstrated modest response rates in select patients, but more importantly showed durable responses from immunotherapy for melanoma." (PMID 36045435, 2022). "A recent landmark report developed a model of adoptive cellular therapy using autologous IL-2 cultures of human tumor infiltrating lymphocytes infused into mice with matched melanoma xenografts." (PMID 36095023, 2022). "Supporting this notion, purified TCR-transgenic anti-GP100 pmel CD8+ T cells expanded in vitro with OMCPmutIL-2 were able to lyse B16 melanoma cells more readily than those expanded in IL-2 or IL-15." (PMID 35603788, 2022). "High doses of interleukin-2 (IL-2) have been used for the treatment of melanoma and renal cell carcinoma, but this therapy has limited efficacy, with a ~15% response rate." (PMID 36059465, 2022). "Rosenberg then applied TIL therapy combined with IL-2 to patients with melanoma and published the first report on the successful treatment of melanoma with TIL-ACT in 1988." (PMID 36077696, 2022). "Administration of the cytokine IL-2, specifically, is considered the first successful human immunotherapy due to its ability to stimulate immunologic clearance of malignancies such as melanoma and renal cell carcinoma in select patients." (PMID 35603788, 2022). "Cytokines such as interleukin 2 (IL-2) and granulocyte-macrophage colony-stimulating factor (GM-CSF) were among the first intratumoral regimens assessed in melanoma." (PMID 33925915, 2021). "As early as the 1980s, high-dose interleukin-2 (IL-2) was used in metastatic renal cell carcinoma and melanoma, leading to persistent responses in a fraction of the treated patients." (PMID 34830973, 2021). "One of the first immunocytokines to make it to clinical trials delivered IL-2 to the GD2 antigen commonly found in melanoma and neuroblastoma tumors." (PMID 33803078, 2021). "A gp100 peptide vaccine with interleukin-2 (IL-2) was shown to have a higher response rate than IL-2 alone in a phase III study of patients with melanoma; however, the overall application of protein/peptide vaccines have been limited thus far." (PMID 34199248, 2021).